PLA2G7 (phospholipase A2 group VII)
Description:
Lipoprotein-associated calcium-independent phospholipase A2 involved in phospholipid catabolism during inflammatory and oxidative stress response. At the lipid-aqueous interface, hydrolyzes the ester bond of fatty acyl group attached at sn-2 position of phospholipids (phospholipase A2 activity). Specifically targets phospholipids with a short-chain fatty acyl group at sn-2 position. Can hydrolyze phospholipids with long fatty acyl chains, only if they carry oxidized functional groups. Hydrolyzes and inactivates platelet-activating factor (PAF, 1-O-alkyl-2-acetyl-sn-glycero-3-phosphocholine), a potent pro-inflammatory signaling lipid that acts through PTAFR on various innate immune cells. Hydrolyzes oxidatively truncated phospholipids carrying an aldehyde group at omega position, preventing their accumulation in low-density lipoprotein (LDL) particles and uncontrolled pro-inflammatory effects. As part of high-density lipoprotein (HDL) particles, can hydrolyze phospholipids having long-chain fatty acyl hydroperoxides at sn-2 position and protect against potential accumulation of these oxylipins in the vascular wall. Catalyzes the release from membrane phospholipids of F2-isoprostanes, lipid biomarkers of cellular oxidative damage.
Synonyms: PAFAH; LDL-PLA2; Lp-PLA2; PAFAD
Tractability: Small molecule: a drug acting on it is in phase 2 or 3 trials; a structure with a bound ligand is known; a high-quality ligand is known; it has a high-quality binding pocket; it belongs to a druggable protein family. Antibody: UniProt places it where antibodies can reach, with high confidence; its Gene Ontology location is reachable by antibodies, with high confidence; UniProt predicts a signal peptide or a membrane-spanning region. PROTAC: ubiquitination databases record sites on it; its protein half-life has been measured; a small molecule that binds it is known.
Target class: Enzyme; Hydrolase
Chemical probes: ML256
Gene: Protein-coding gene on chromosome 6 (46,704,201 to 46,735,718, reverse strand). Ensembl gene ENSG00000146070.
Subcellular location: Secreted, extracellular space
Pathways (Reactome):
Metabolism of proteins: Synthesis, secretion, and deacylation of Ghrelin
Gene Ontology:
Molecular function: 1-alkyl-2-acetylglycerophosphocholine esterase activity; phospholipase A2 activity; phospholipid binding; protein binding; hydrolase activity, acting on ester bonds
Biological process: lipid oxidation; low-density lipoprotein particle remodeling; phosphatidylcholine catabolic process; plasma lipoprotein particle oxidation; platelet activating factor catabolic process; platelet activating factor metabolic process; positive regulation of lipid transport; positive regulation of monocyte chemotaxis; peptide hormone processing; positive regulation of inflammatory response
Cellular component: high-density lipoprotein particle; low-density lipoprotein particle; extracellular region
Genetic constraint (gnomAD): Loss-of-function variants: 27 observed, 24.26 expected, observed/expected ratio (o/e) 1.11, 90% interval 0.82 to 1.53. The upper end of that interval is the gene's LOEUF score, 1.53, which puts it in group 6 of 6, group 1 being the genes least tolerant of losing a copy. Missense variants: 270 observed, 236.75 expected, observed/expected ratio (o/e) 1.14, 90% interval 1.03 to 1.26. Synonymous variants: 96 observed, 79.69 expected, observed/expected ratio (o/e) 1.2, 90% interval 1.02 to 1.43.
Homologues: Orthologues: chimpanzee PLA2G7 (99% identical), macaque PLA2G7 (94% identical), rabbit PLA2G7 (83% identical), pig PLA2G7 (80% identical), dog PLA2G7 (72% identical), rat Pla2g7 (68% identical), mouse Pla2g7 (68% identical), guinea pig PLA2G7 (66% identical), zebrafish pla2g7 (49% identical), tropical clawed frog pla2g7 (48% identical), Caenorhabditis elegans paf-2 (28% identical), Caenorhabditis elegans paf-1 (27% identical). Paralogues in human: PAFAH2 (37% identical).
Diseases named in the same sentence as PLA2G7 in open-access papers:
PLA2G7 is named in the same sentence as 221 diseases in open-access papers, as found by Europe PMC text mining. Sharing a sentence is not in itself a finding about the gene and the disease. The quoted sentences say what the papers report.
atherosclerosis (160 papers, 2007 to 2026). A disease characterized by the build-up of fatty material and calcium deposition in the arterial wall resulting in partial or complete occlusion of the arterial lumen. "PLA2G7 has been associated with atherosclerosis, diabetes, and cardiovascular disease, and considered as a potential target that is a nexus between the immune, metabolic, and cardiovascular pathways of aging." (PMID 38575325, 2024). "Given these knowledge gaps, our pilot study aimed to investigate the impact of the PLA2G7 R92H polymorphism on clinical atherosclerosis." (PMID 39712681, 2024). "Whilst there is no available information on the effect of PLA2G4A variants on atherosclerosis measurements, there are some previous reports linking PLA2G7 SNPs to this pathology." (PMID 35586043, 2022). "To elaborate, PLA2G7 is associated with an increased risk of atherosclerosis,cardiac aging, diabetes mellitus, autoimmune disease, and neoplastic conditions -suggesting a role in both metabolic and immune pathways." (PMID 35497092, 2022). "Downregulation of the expression of the PLA2G7 gene by RNA interference has also been shown to ameliorate inflammation and atherosclerosis in mice deficient in apo-lipoprotein E." (PMID 35694871, 2022). "Single nucleotide polymorphisms (SNPs) in the PLA2G7 gene have emerged as potential genetic risk factors that may increase susceptibility to atherosclerosis and subsequent CAD." (PMID 39712681, 2024). "PLA2G4A and PLA2G7 harboured several SNPs associated with atherosclerosis measurements in the patients, namely common carotid intima media thickness (ccIMT), presence of plaques, number of plaques detected and 2-years ccIMT progression (significant p-values ranging from 0.0004 to 0.047)." (PMID 35586043, 2022). "Downregulation of the acetylhydrolase PLA2G7 may result in an increased risk for atherosclerosis, though the role of this enzyme in this field is still contentious." (PMID 20546557, 2010). "The significance of PLA2G7 is evident across a range of metabolic and inflammatory diseases, including atherosclerosis, diabetes, and autoimmune disorders." (PMID 41030501, 2025). "The PLA2G7 enzymatic activity generates bioactive lipid mediators, which play roles in atherosclerosis and tumor progression." (PMID 40136470, 2025). "For example, we found that PLA2G7 which lowers healthspan is targeted by PLA2G7 inhibitors which are currently used in the treatment for atherosclerosis and Alzheimer disease." (PMID 38575325, 2024). "PLA2G7 has been primarily studied in its role in atherosclerosis, and an inhibitor of PLA2G7 activity, darapladib, has been proposed as a therapeutic target for atherosclerosis." (PMID 38016942, 2023). "Previously, PLA2G7 has beenassociated with atherosclerosis, diabetes, and cardiovascular disease, and as a marker of cardiacaging, thus this study willinterest the cardiovascular aging scientific community." (PMID 35497092, 2022). "A number of PLA2G7 single nucleotide polymorphisms (SNPs) have been associated with Lp-PLA2 activity and atherosclerosis." (PMID 35586043, 2022). "Our goal was to determine whether genetic variability in three candidate phospholipase-related genes, namely PLA2G7, SCARB1 and PLA2G4A, was associated with atherosclerosis and the occurrence of CV events in a population of nephrosclerosis patients." (PMID 35586043, 2022). "Lp-PLA2 (Pla2g7) was upregulated in COX-2-/- cells and plaque forming inflammatory cells in atherosclerosis." (PMID 27012456, 2016). "Therefore, PLA2G7 has been extensively studied in many inflammatory diseases, and the PLA2G7 inhibitors darapladib or rilapladib have already been tested in Phase II and Phase III clinical trials for treatment of Alzheimer's disease, diabetic retinopathy, and atherosclerosis." (PMID 34427055, 2021).
coronary heart disease (108 papers, 2007 to 2025). "The mutations on PLA2G7 gene have been reported to be associated with coronary artery disease since 15 years ago and some alleles had been proved to increase the risk of coronary heart disease." (PMID 28903366, 2017). "PLA2G7 rs1051931 polymorphisms were found to be associated with coronary artery disease." (PMID 32656171, 2020). "PLA2G7 gene has been widely studied as a candidate risk factor of coronary heart disease." (PMID 27716781, 2016). "PLA2G7 gene product is a secreted enzyme whose activity is associated with coronary heart disease (CHD)." (PMID 23555769, 2013). "In recent years, PLA2G7 has been extensively studied in the context of cardiovascular diseases, with the PLA2G7 inhibitor darapladib being investigated for the prevention and treatment of coronary heart disease." (PMID 40169540, 2025). "PLA2G7 hydrolyzes oxidized phospholipids in LDL particles, and its enzymatic activity is associated with a risk of coronary heart disease and ischemic stroke." (PMID 40136470, 2025). "Previous research has established a strong link between the PLA2G7 gene and the development of coronary artery disease (CAD)." (PMID 39712681, 2024). "The rs1805017 G and rs1051931 A alleles of PLA2G7 gene were found to be associated with coronary artery disease (CAD) yet, up to now, studies are inconclusive on the association between PLA2G7 variants and cardiovascular risk." (PMID 25889305, 2015). "In addition, lipoprotein-associated PLA2 (Lp-PLA2) encoded by PLA2G7 is abundant in coronary atherosclerotic plaques and elevated levels of this enzyme are associated with coronary heart disease events in healthy older adults." (PMID 36293289, 2022). "Our top SNP associated with mass was also a common non-synonymous variant (H92R) in PLA2G7, and has not previously been associated with Lp-PLA2 activity or mass, but has been associated with coronary artery disease." (PMID 20442857, 2010).
diabetes (88 papers, 2010 to 2026). "Genetically predicted PLA2G7 had null association with diabetes, CKD, and eGFR." (PMID 41775939, 2024). "This is in agreement with the known function of PLA2G7 in cardiovascular diseases and previous results with PLA2G7 inhibitor treatment showing significant decrease in LPC levels in the arteries of pigs with induced diabetes and hypercholesterolemia." (PMID 22202492, 2011). "Besides, hypertension and diabetes are linked by CXCL8, HLA-B, and KANSL1; diabetes and obesity are linked by TRIM26 and MMP8; hypertension and obesity are linked by PLA2G7, FSTL3, STC2, and BCL2A1." (PMID 36685671, 2023). "Female cases had a higher PLA2G7 methylation level than female controls while it was the opposite in males, although the latter comparison was not significant after correction with confounding factors such as smoking and status of diabetes and hypertension." (PMID 23555769, 2013). "So we speculate that environmental factors such as aging, smoking, diabetes and hypertension may play their roles in the risk of CHD through affecting PLA2G7 methylation." (PMID 23555769, 2013). "It has recently been demonstrated that adipose tissue from individuals with type 2 diabetes has higher levels of PLA2G7 gene expression compared with that observed in individuals without diabetes." (PMID 34562103, 2022). "The correlation between PLA2G7 methylation and CHD risk in females is independent of other parameters including age, smoking, diabetes and hypertension." (PMID 23555769, 2013).
Stroke (74 papers, 2007 to 2025). Sudden impairment of blood flow to a part of the brain due to occlusion or rupture of an artery to the brain. "PLA2G7 encodes plasma PAF acetylhydrolase (PAF-AH), an extracellular Lp-PLA2, whose activity is related to large-artery atherosclerotic etiology and recurrent stroke in transient ischaemic attack patients." (PMID 32656171, 2020).
Hypertension (45 papers, 2010 to 2025). The presence of chronic increased pressure in the systemic arterial system. "However, the 32% lower Lp-PLA2 activity detected in PLA2G7 279F allele carriers might offer certain protection against hypertension, even in the case of persistent overweight for more than three years." (PMID 28334001, 2017). "These interactive effects between PLA2G7 V279F and baseline BMI indicate that the approximately 32% lower Lp-PLA2 activity detected in the PLA2G7 279F allele carriers might offer certain protection against hypertension, even in the case of persistent overweight for over three years." (PMID 28334001, 2017).
metabolic syndrome (36 papers, 2008 to 2025). A cluster of metabolic risk factors for CARDIOVASCULAR DISEASES and TYPE 2 DIABETES MELLITUS. "Some reports also showed significant increases in Pla2g7 mRNA expression in the liver of metabolic syndrome rats." (PMID 30302116, 2018).
myocardial infarction (29 papers, 2010 to 2026). Gross necrosis of the myocardium, as a result of interruption of the blood supply to the area, as in coronary thrombosis. "In this study, the largest to date to explore the association between the PLA2G7 V279F variant and CAD, we provide consistent evidence that this null allele offers a significant protection against CAD, in particular myocardial infarction, in Korean males." (PMID 21490708, 2011).
endothelial dysfunction (26 papers, 2010 to 2025). In vascular diseases, endothelial dysfunction is a systemic pathological state of the endothelium (the inner lining of blood vessels) and can be broadly defined as an imbalance between vasodilating and vasoconstricting substances produced by (or acting on) the endothelium. "In humans, increased activities of certain variants of PLA2G7 were associated with early coronary atherosclerosis and with endothelial dysfunction, but the gene may also exert an anti-inflammatory function." (PMID 22905720, 2012).
type 2 diabetes (23 papers, 2012 to 2025). "Analysis of PLA2G7 gene expression in AbdSc adipose tissue depots from lean, obese and type 2 diabetic individuals showed a significant increase in diabetic adipose tissue compared with lean adipose tissue (p < 0.01)." (PMID 29427237, 2018).
Obesity (21 papers, 2010 to 2026). Accumulation of substantial excess body fat. "Genetic deletion or pharmacological suppression of PLA2G7 was found to reduce obesity-associated COPD-like pathology." (PMID 41652631, 2026). "CONCLUSIONS: PLA2G7 acts as a key mediator of obesity-associated COPD and represents a promising therapeutic target for preventing obesity-related lung injury." (PMID 41652631, 2026). "Transcriptomic analysis of lung tissues from obesity-associated COPD patients and obese mice identified macrophage-derived phospholipase A2 group VII (PLA2G7) as a key regulator of disease pathogenesis." (PMID 41652631, 2026). "A higher expression of PLA2G2D, PLA2G4A and PLA2G7 were found in scWAT of individuals living with healthy obesity." (PMID 38024342, 2023). "In mice, obesity and a high-fat diet increased Pla2g7 expression, but caloric restriction reduced the expression." (PMID 36809973, 2023). "METHODS: To investigate the role of PLA2G7 in obesity-related chronic obstructive pulmonary disease (COPD), we employed clinical specimens as well as in vivo and in vitro models, integrating multi-omics approaches with genetic and pharmacological interventions." (PMID 41652631, 2026).
Alzheimer disease (20 papers, 2010 to 2026). A progressive, neurodegenerative disease characterized by loss of function and death of nerve cells in several areas of the brain leading to loss of cognitive function such as memory and language. "Darapladib and rilapladib are potent reversible inhibitors of PLA2G7 that have previously been tested in large cohorts of patients for treatment of various pathologies including cardiovascular diseases, diabetic retinopathy, and Alzheimer's disease." (PMID 34427055, 2021).
Cognitive impairment (15 papers, 2016 to 2025). Abnormal cognition is characterized by deficits in thinking, reasoning, or remembering. "Most importantly, plasma APOE, MMP9, S100A8, UBR5 PLA2G7, and STAT5B play a potentially crucial role in the progression of cognitive disorders." (PMID 38883967, 2024).
COVID-19 (15 papers, 2021 to 2026). A disease caused by infection with severe acute respiratory syndrome coronavirus 2. "The serum protein level of Lp-PLA2 (or PLA2G7) was found to be elevated in COVID-19 subjects and its expression was highly induced in macrophages in the lung." (PMID 38276214, 2024). "An increase in another sPLA2 isoform encoded by the PLA2G7 gene, lipoprotein-associated phospholipase A2 (Lp-PLA2), has also been detected in the sera of patients with COVID-19." (PMID 37189799, 2023). "Pro-inflammatory macrophages in lungs emerging with progression of COVID-19 show predominantly increased PLA2G7 expression." (PMID 35091537, 2022). "Taken together, PLA2G7 which was revealed as a biomarker in COVID-19 by integrated hypothesis-free single biomarker analysis, provided alternative insights into prevalence of cardiovascular involvements seen in COVID-19 patients and patho-mechanism underlying COVID-19." (PMID 33762651, 2021). "PLA2G7 was further found to be predominantly expressed by proinflammatory macrophages in lungs emerging with progression of COVID-19." (PMID 33762651, 2021). "Serum protein levels of PLA2G7 were found to be elevated and beyond the normal limit in COVID-19 patients, especially among those re-positive patients." (PMID 33762651, 2021). "Although the long-term health effects of role of PLA2G7 in COVID-19 cannot yet be determined, on-going epidemiological evidence substantiated heart issues were occurred after COVID-19." (PMID 33762651, 2021). "On the whole, PLA2G7 was predominantly expressed by monocyte-derived proinflammatory macrophages emerging along with progression of COVID-19." (PMID 33762651, 2021). "The positive rate of PLA2G7 were correlated with not only viral loads but also severity of pneumonia in non-COVID-19 patients." (PMID 33762651, 2021). "In the validation stage, RNA level of PLA2G7 was identified in nasal swabs from both COVID-19 and pneumonia patients, other than health individuals." (PMID 33762651, 2021). "Furthermore, strong correlation between expression of PLA2G7 and the severity of COVID-19 was found (r = 0.927, P value = 1.4e − 4)." (PMID 33762651, 2021). "This was consistent with our findings that expression of PLA2G7 was correlated with severity of COVID-19, suggesting PLA2G7 could be also used to monitor the progression of pneumonia." (PMID 33762651, 2021). "PLA2G7 could be a potential prognostic and therapeutic target in COVID-19." (PMID 33762651, 2021). "We identified and validated PLA2G7, a biomarker for CVD, was abnormally enhanced in COVID-19 at both nucleotide and protein aspects." (PMID 33762651, 2021). "Thereafter, we next explored the relationship between positive rates of PLA2G7 and viral load of SARS-CoV-2 in COVID-19 group." (PMID 33762651, 2021). "The gene expression of PLA2 isoforms, PLA2G4A and PLA2G5, were upregulated, while PLA2G6 and PLA2G7 were downregulated in COVID-19 patients using GCs, compared to non-treated COVID-19 patients and controls." (PMID 36851787, 2023). "Here we identified phospholipase A2 group VII (PLA2G7), a well-studied CVD biomarker, as a hub gene in COVID-19 though an integrated hypothesis-free genomic analysis on nasal swabs (n = 486) from patients with COVID-19." (PMID 33762651, 2021). "The PLA2G7 was not validated in nasal swabs from the patients with severe COVID-19." (PMID 33762651, 2021).